Y_RNA (Y RNA )
Gene: Miscellaneous RNA gene on chromosome 15 (37,050,828 to 37,050,930, reverse strand). Ensembl gene ENSG00000206676.
Homologues: Orthologues: chimpanzee Y_RNA (100% identical), macaque Y_RNA (100% identical), guinea pig Y_RNA (86% identical). Paralogues in human: Y_RNA (85% identical), RNY3 (84% identical), Y_RNA (84% identical), Y_RNA (83% identical), RNY3P1 (82% identical), RNY3P14 (82% identical), Y_RNA (82% identical), RNY3P11 (81% identical), Y_RNA (81% identical), RNY3P16 (80% identical), RNY3P9 (80% identical), Y_RNA (80% identical), and 92 more.